KIF11 (kinesin family member 11)
Diseases named in the same sentence as KIF11 in open-access papers (continued):
Sharing a sentence is not in itself a finding about the gene and the disease.
microcephaly (25 papers, 2015 to 2026). A congenital or acquired developmental disorder in which the circumference of the head is smaller than normal for the person's age and sex. "Here we report the case of a patient with microcephaly, lymphedema, nystagmus and familial exudative vitreoretinopathy carrying a novel de novo KIF11 nonsense variant (NM_004523.4:p.Glu123Ter), which is considered pathogenic." (PMID 41771856, 2026). "The KIF11 mutation was found in 75% of patients with microcephaly in clinical samples; KIF14 mutations have also been reported in patients." (PMID 40964093, 2025). "Here, we document a longstanding follow-up of a case of MCLMR associated with a novel, de novo KIF11 mutation presenting with microcephaly, developmental delay, CRA, and bilateral RD, for which both surgical and expectant management were utilized." (PMID 40426739, 2025). "Pathogenic variants in kinesin KIF11 underlie microcephaly-lymphedema-chorioretinopathy (MLC) syndrome." (PMID 41427784, 2025). "The pathogenic variants in KIF11 were first identified in patients with microcephaly, chorioretinal dysplasia, and primary lymphedema syndrome (MCLMR, OMIM 152950)." (PMID 36672954, 2023). "Several previous studies found that some patients with FEVR carrying KIF11 variants also had syndromic features, such as microcephaly and mental retardation, indicating a complex phenotypic overlap between MCLMR and FEVR." (PMID 36672954, 2023). "Spontaneous mutation of KIF11 took over the majority, accompanied by microcephaly and choroidal atrophy." (PMID 35918671, 2022). "Heterozygous mutations in KIF11 lead to abnormal lymphedema in microcephaly, lymphedema, and chorioretinal dysplasia (MLCRD)." (PMID 36742345, 2022). "Among them, two missense mutations (p.S235C and p.H244Y) in KIF11 were previously identified in two unrelated patients with severe hearing loss in addition to chorioretinopathy and microcephaly." (PMID 34912366, 2021). "In HGMA, 100 different variants in KIF11 are linked to several conditions, such as microcephaly, lymphoedema, chorioretinopathy, and hearing loss." (PMID 34912366, 2021). "A frame-shift mutation in the KIF11 gene was identified in patient 4, who was known to have microcephaly and retinopathy, consistent with the phenotype." (PMID 26846091, 2016). "The most frequent clinical signs and symptoms in patients with a KIF11 mutation are microcephaly (91%), eye anomalies (72%) and intellectual disability (67%)." (PMID 25934493, 2015). "No additional pathogenic variants were identified in genes associated with the patient’s systemic or ocular phenotype, including KIF11 and other genes commonly implicated in microcephaly and chorioretinopathy syndromes, as well those linked to the FEVR spectrum." (PMID 40405340, 2025). "Although it is more common to find information on Eg5 and cancer when searching in common research motors (PubMed, Scopus), there are many available papers in which Eg5/KIF11 mutations are associated with microcephaly, and in particular, with MCLID and retinal pathological conditions, such as FEVR." (PMID 38939361, 2024). "Kinesin family member 11 (KIF11)-associated disorder, a rare condition caused by autosomal dominant mutations in the KIF11 gene, presents with microcephaly, chorioretinal dysplasia, lymphoedema, and varying degrees of intellectual disability." (PMID 39359715, 2024). "KIF11 alterations are responsible for some specific conditions, such as microcephaly and retinopathies." (PMID 38939361, 2024). "The retinal phenotype observed in our patients shows overlap with KIF11-related retinopathy and other forms of microcephaly and chorioretinopathy syndrome, which similarly present with microcephaly, microphthalmia, peripheral retinal avascularity, and tractional retinal detachments." (PMID 40405340, 2025).
microcephaly (continued). "KIF11 mutations are thought to be responsible for all inherited, and nearly half of sporadic, cases of microcephaly with or without chorioretinopathy, lymphedema or impaired intellectual development (MCLMR; OMIM 152950)." (PMID 40426739, 2025). "Several of these genes are implicated in systemic disorders that can feature retinal involvement, including KIF11 (microcephaly–lymphedema–chorioretinal dysplasia), COL11A1 (Stickler syndrome), PHYH (Refsum disease), and TUBB4B (Leber congenital amaurosis with early-onset deafness)." (PMID 40923693, 2025). "Notably, mutations in the genes encoding kinesin motors-KIF1B, KIF14, KIF16B, KIF11, KIF10, KIF15, and KIF2A-have been identified in numerous patients with microcephaly." (PMID 38218748, 2024). "KIF-11 variants are also associated with several medical conditions including microcephaly, lymphedema, and chorioretinal dysplasia (MLCRD) as well as chorioretinal dysplasia, microcephaly, and mental retardation (CDMMR)." (PMID 35328049, 2022). "All disorders related to these genes include ADHD among their clinical manifestations: KIF11 is responsible for a disorder with microcephaly and lymphedema (OMIM #152950), WAC for Desanto-Shinawi syndrome (#616708), and CRBN is responsible for a recessive intellectual disability syndrome (#616708)." (PMID 35052433, 2021). "In 2012, mutations in KIF11 were found to be associated with the development of a rare autosomal dominant inheritable disease called microcephaly with or without chorioretinopathy, lymphedema, or mental retardation (MCLMR) (OMIM 152950)." (PMID 27212378, 2016). "KIF11 gene mutations cause a rare autosomal dominant inheritable disease called microcephaly with or without chorioretinopathy, lymphedema, or mental retardation (MCLMR)." (PMID 27212378, 2016). "For Patient 2, initial genomic analysis using the clinical pipeline did not identify any pathogenic variants in KIF11 and other genes commonly implicated in microcephaly and chorioretinopathy syndromes, nor in genes associated with FEVR or inherited retinal disease." (PMID 40405340, 2025). "KIF11 heterozygous nonsense mutations cause microcephaly with or without chorioretinopathy, lymphedema, or mental retardation (OMIM: 152950), while PIEZO1 homozygous or compound heterozygous loss-of-function mutations cause lymphatic malformations 6 (OMIM: 616843)." (PMID 35806420, 2022). "The phenotype of the KIF11 mutation-negative sporadic patients may be due to non-detected germline or mosaic KIF11 mutations and/or defects in (a) gene(s) causing (a) mimicking disorder(s), as microcephaly and primary lymphedema are genetically highly heterogeneous." (PMID 25934493, 2015). "Reduced Eg5 activity, due to mutations of KIF11 gene, is also responsible for pathological conditions such as microcephaly with or without chorioretinopathy, lymphedema, or intellectual disability (MCLRI) and familial exudative vitreous retinopathy (FEVR)." (PMID 38939361, 2024). "A rare condition known as kinesin family member 11 (KIF11)-associated disorder, with a prevalence lower than 1 in 1,000,000, is characterised by varying expressions of microcephaly, either with or without chorioretinal dysplasia, along with lymphoedema and learning disabilities." (PMID 39359715, 2024). "Similarly, mutation of KIF11, a microtubule-based motor protein, results in MLCRD (microcephaly with or without chorioretinopathy, lymphedema, or mental retardation, OMIM #152950) syndrome." (PMID 34055805, 2021).
glioblastoma (23 papers, 2009 to 2025). The most malignant astrocytic tumor (WHO grade IV). "In glioblastoma, upregulation of KIF11 by attenuating protein turnover plays an important role in the motility and morphogenesis of proliferating cells and affects microtubule dynamics by maintaining microtubule polymerization." (PMID 33995648, 2021). "KIF11 was also highly expressed in glioblastoma, especially in proliferating and migrating cells, and targeting of KIF11 with a small-molecule inhibitor pronouncedly inhibited initiation and self-renewal of cancer stem cells." (PMID 33995648, 2021). "KIF11 was identified as a molecular target that shuttles between the proliferation and invasion of glioblastoma." (PMID 32322170, 2020). "We previously demonstrated that there is an interphase pool of KIF11 present in glioblastoma cancer stem cells that drives tumor cell invasion." (PMID 32811879, 2020). "Inhibition of KIF11 with a highly specific small‐molecule inhibitor has been proven to delay the growth of commonly treatment‐resistant glioblastoma tumor cells and to hamper tumor initiation." (PMID 32346924, 2020). "Administration of KIF11 inhibitors in glioblastoma-bearing mice had a significantly extended survival indicating a putative therapeutic target for glioblastoma." (PMID 32322170, 2020). "In the current study, mitotic kinesin KIF11, which is required for the separation of duplicated centrosomes and for the spindle formation, was deemed to be a promising target for glioblastoma treatment." (PMID 19545421, 2009). "In this study we combined chemical, in silico ADME and PK properties and biological approaches to analyze the effect of a pannel of mitotic kinesin KIF11 inhibitors on Glioblastoma cell lines." (PMID 19545421, 2009). "The expression profile of KIF11 mRNA in glioblastoma cells versus normal astrocytes was first assessed." (PMID 19545421, 2009). "Moreover, KIF11 expression is significantly higher in glioblastoma cells compared to normal cells, and there is also an overexpression of Hedgehog signaling in glioblastoma." (PMID 38218748, 2024). "Furthermore, lower expression level of KIF11 was associated with clinical benefits of programmed death receptor-1 (PD-1) ICB therapy in patients with melanoma and glioblastoma." (PMID 36742345, 2022). "Treatment of glioblastoma cells with a haemagglutinating virus vector HAJ-E containing siRNA targeting the mitotic motor protein KIF11 (kinesin family member 11, also known as EG5) led to the formation of a monopolar division spindle, cell cycle arrest, and apoptosis." (PMID 35846075, 2022). "Furthermore, lower expression level of KIF11 was associated with clinical benefits of PD-1 ICB therapy in melanoma and glioblastoma." (PMID 36742345, 2022). "KIF11 has also been identified as a molecule involved in pancreatic cancer, non–muscle invasive bladder urothelial carcinoma, non–small cell lung cancer, and glioblastoma." (PMID 32346924, 2020). "Glioblastoma (GBM) is a deadly brain tumor, and the kinesin motor KIF11 is an attractive therapeutic target with roles in proliferation and invasion." (PMID 38652658, 2024). "In particular, KIF11, known as Eg5 or kinesin spindle protein (KSP), being overexpressed in gastric, breast, pancreatic, prostate, and bladder cancers and glioblastoma, is worthy of in-depth investigation." (PMID 35164221, 2022). "Analysis of essential regulators of the G2/M and spindle assembly checkpoints (PLK1, TTK/MPS1), mitotic spindle dynamics (KIF11) and sister chromatid separation (PTTG1/securin) confirmed their down-regulation in a panel of glioblastoma cell lines." (PMID 33478100, 2021). "We further focused on KIF11 and KIF20A expression in glioblastoma and found general over-expression in this pathology in two additional studies." (PMID 24327603, 2013).
glioblastoma (continued). "While resistance to Kif11 inhibitors in other cell types is due to mechanisms that prevent these drugs from disrupting mitosis, we find that in glioblastoma (GBM), resistance to the Kif11 inhibitor ispinesib works instead through suppression of apoptosis driven by activation of STAT3." (PMID 35732128, 2022). "Additionally, we have previously studied a non-mitotic role for KIF11 in the context of glioblastoma (GBM)." (PMID 32811879, 2020).
lymphedema (22 papers, 2013 to 2026). Excess fluid collection in tissues, causing swelling. "Previous studies have found that KIF11 is closely associated with familial exudative vitreoretinopathy, lymphedema, intellectual disability, chorioretinopathy, and an increased risk of T2DM." (PMID 38915894, 2024). "We recommend that, when identifying a KIF11 mutation, the patient is followed by both an ophthalmologist experienced in the disease and a paediatrician for monitoring potential lymphoedema and other general problems." (PMID 39359715, 2024). "Recent insight from genetic studies further support the notion that KIF11 is required for development of normal retinal and lymphatic vessels, since KIF11 mutations cause autosomal-dominant microcephaly associated with lymphedema and/or chorioretinopathy." (PMID 24327603, 2013). "Although well known for regulating spindle dynamics ensuring successful cell division, the association of KIF11 (encoding EG5) with development of the lymphatic system and how KIF11 pathogenic variants lead to lymphatic dysfunction and lymphedema remain unknown." (PMID 41427784, 2025). "Mutations in the KIF11 gene are known to cause autosomal dominant inherited microcephaly with or without chorioretinopathy, lymphedema, or mental retardation, a phenotype that is consistent with the clinical features of the patient in which we identified a KIF11 mutation." (PMID 26846091, 2016). "Microcephaly with or without chorioretinopathy, lymphedema or mental retardation is a rare KIF11-related disorder." (PMID 41771856, 2026). "The protein encoded by kinesin family member 11 (KIF11) can cause autosomal dominant microcephaly with or without chorioretinopathy, lymphedema or intellectual disability." (PMID 36411543, 2022).
hepatocellular carcinoma (21 papers, 2013 to 2026). A malignant tumor that arises from hepatocytes. "According to recent studies, KIF11 is overexpressed in various cancers and is associated with poor prognoses, including hepatic carcinoma." (PMID 39764737, 2025). "We found that KIF11 deficiency increased the proportion of SA‐β‐Gal positive hepatoma cells and the formation of heterochromatin foci in the nucleus of HepG2 cells." (PMID 37752791, 2023). "More importantly, through rescue experiments, it was found that KIF11 overexpression reversed the senescence phenotype in hepatoma cells caused by NEAT1 deletion." (PMID 37752791, 2023). "KIF11 is also regulated through wnt signaling pathway and associated with recurrence of hepatocellular carcinoma." (PMID 34675265, 2021). "Recent researches reported that KIF11 was overexpressed in several tumors and associated with the poor prognosis, such as prostate cancer, gastric cancer, non-small cell lung cancer, oral cancer, meningioma, hepatic carcinoma, and pancreatic tumor." (PMID 33490265, 2021). "Furthermore, KIF11 knockdown caused senescence in cultured hepatoma cells." (PMID 37752791, 2023). "Hepatocellular carcinoma (HCC) is one of the cancer forms possessing the highest correlation with KIF11 overexpression." (PMID 38939361, 2024). "First, in vitro experiments show that knockdown KIF11 inhibited clone formation and tumour‐spheres formation of hepatoma cells." (PMID 37752791, 2023). "It is reported that KIF11 is capable of predicting poor prognosis of hepatocellular carcinoma, the expression level of which is correlated with tumor staging." (PMID 37656243, 2023). "We established a KIF11 stably depleted hepatoma cell line, through cell-cloning experiments and cell counting kit-8 (CCK-8) assays to detect the effects on proliferation in vitro." (PMID 33490265, 2021). "And then, we clarified the relationship between the expression of KIF11 and the prognosis and clinicopathological characteristics of hepatocellular carcinoma." (PMID 33490265, 2021). "In this study, firstly, we revealed the expression of KIF11 in hepatocellular carcinoma through analyzing TCGA database and IHC staining of patient specimens." (PMID 33490265, 2021). "Furthermore, KIF11 is negatively corelated with p16 and p14 in cultured liver cells and hepatoma cells." (PMID 37752791, 2023). "This indicates that the effect of NEAT1 on hepatoma cell senescence is dependent on KIF11." (PMID 37752791, 2023). "We then detected the changes of KIF11 in senescent hepatoma cells." (PMID 37752791, 2023). "Next, a literature search was conducted to focus on proteins specifically associated with liver disease in general, which selected 20 proteins, seven of which (i.e., CEP55, CLIC1, EPS15L1, G6PD, KIF11, SLC1A5, and TK1) were found to be specifically associated with hepatocellular carcinoma." (PMID 37627157, 2023). "Likewise, KIF11 was highly expressed in cultured hepatoma cells (HCCLM3, Huh7, HepG2 and SNU398) compared with normal liver cells (HLSEC and THLE‐3)." (PMID 37752791, 2023). "Finally, we use in vivo and in vitro experiments to verify the expression of hepatocellular carcinoma after knockdown KIF11." (PMID 33490265, 2021). "Among them, CDK1, CHEK1, TYMS, KIF11, MMP12, TK1 and CA12 were differentially highly expressed in hepatocellular carcinoma tissues." (PMID 38842135, 2024). "Altogether, KIF11 negatively correlates with senescence in both clinical HCC tissues and cultured hepatoma cells." (PMID 37752791, 2023). "High expression of NEAT1 or KIF11 inhibits hepatocellular senescence in clinical HCC and cultured hepatoma cells." (PMID 37752791, 2023). "Knockdown NEAT1 or KIF11, serum starvation, H2O2 or DOXO treatment are the ways to induce senescence in hepatoma cells." (PMID 37752791, 2023). "During senescence, NEAT1 translocated into cytosol and interacted with a motor protein KIF11, resulting in KIF11 protein degradation and subsequent increased expression of CDKN2A in cultured hepatoma cells." (PMID 37752791, 2023).
hepatocellular carcinoma (continued). "Based on our discovery, NEAT1 and KIF11 are overexpressed in HCC tissues and hepatoma cells, and both are negatively correlate with senescence." (PMID 37752791, 2023). "It has also been reported that PRC1 controls the expression and function of wrrag such as FANCI, SPC25, KIF11, and KIF23 via Wnt signaling in hepatocellular carcinoma (HCC)." (PMID 40400636, 2025). "Upregulated KIF11 has been identified in various cancers, such as in glioma, adrenocortical carcinoma (ACC), colorectal cancer (CRC), non-small-cell lung cancer (NSCLC), and hepatocellular carcinoma (HCC), and is related to poor prognosis." (PMID 38672404, 2024).
lung carcinoma (19 papers, 2015 to 2025). "KIF11 is also identified as a key gene in the development of BPDE‐associated lung cancer and a potential target for lung cancer prevention and treatment." (PMID 40925573, 2025). "We analyzed lung cancer cohorts with KRAS mutations (GSE31210) and found that higher hub gene levels (BUB1, BUB1B, NCAPG, CDC20, CDK1, KIF11) were significantly associated with worse OS in lung cancer patients with KRAS mutations." (PMID 36176446, 2022). "In this study, we found that the expression of BUB1, CCNA2, CDC20 and KIF11 increased after inhibitor resistance compared with inhibitor-sensitive lung cancer samples, and these targets were associate with cell cycle, cell proliferation, DNA damage and EMT." (PMID 36176446, 2022). "Previous studies have reported that KIF11 was up-regulated in lung cancer tissues compared with normal tissues, and associated with poor overall survival." (PMID 32411535, 2020). "We confirmed that three kinesin genes (KIF4A, KIF20A, and KIF11) have some influence on the occurrence and progression of lung cancer." (PMID 41462522, 2025). "In addition, the expression level of main hub genes (BUB1, CCNA2, CDC20, KIF11) was significantly higher in patients with EGFR TKI-resistant lung cancer tissues (GSE161584) than EGFR TKI-sensitive lung cancer tissues." (PMID 36176446, 2022). "The roles of KIF4A, KIF11 and KIF2C in lung cancer have been already reported, while the involvement of KIF20A in LUAD remains largely unknown." (PMID 30105795, 2018).